TNF (tumor necrosis factor)
Diseases named in the same sentence as TNF in open-access papers (continued):
Sharing a sentence is not in itself a finding about the gene and the disease.
periodontitis (continued). "Periodontitis-induced free radicals and proinflammatory cytokines (IL6, IL17, TNF, CRP) can even activate the hepatocytes and increase CRP production, increasing the systemic inflammatory burden and AGE formation." (PMID 35625570, 2022). "VCO gel can affect the expression of TNF-α and TGF-β1 in the regeneration process of periodontal tissue in periodontitis-induced rats." (PMID 35178093, 2022). "OBMCs and PBMCs of periodontitis patients were left untreated or treated with IL-2 or IFN-γ or PMA/I, and the levels of TNF-α secretion were determined after 12 to 18 h." (PMID 33672708, 2021). "However, during periodontitis, the immune response is a double-edged sword because the cytokines and antimicrobial components produced during the immune response, such as IL-17, IL-6, IL-1β, TNF-α, ROS, and NETs, can induce bone resorption and soft tissue injury." (PMID 33777839, 2021). "In patients with periodontitis, the present study observed increased levels of pro-inflammatory factors IFN-γ, IL-1β, IL-2, IL-7, IL-21, and TNF-α, in addition to decreased levels of anti-inflammatory factors IL-5 in GCF of T2DM patients." (PMID 33417619, 2021). "TNF-α, CCL2, IL-6, IFN-γ, and CXCL8 showed significantly higher levels in GCF from periodontitis patients compared to control subjects (p < 0.05)." (PMID 34502071, 2021). "Serum‐based IL‐6, TNF‐α and IL‐1β, three different cytokines expression were demonstrated in PBMC of periodontitis and healthy controls." (PMID 34272761, 2021). "With the ability of keratinocytes to secrete TNF-α, research in the past decade pointed towards TNF-α as a key regulatory factor in the pathogenesis of oral lichen planus and periodontitis." (PMID 34199238, 2021). "Matrix metalloproteinase‐8 (MMP‐8), MMP‐9, and tumor necrosis factor alpha (TNF‐α) levels were higher in periodontitis and in RA and MMP‐8 levels increased with the severity of periodontitis." (PMID 33954982, 2021). "Existing studies have compared the expression differences in TNF-α, IL-6, IFN-γ, IL-17 and IL-23 in GCF of T2DM patients and systemically healthy subjects with periodontitis, which were higher in the former group." (PMID 33417619, 2021). "De Molon reported that the gene and protein expressions of IL-1β, IL-6, and TNF-α are involved in osteoclastogenesis, as well as in the production of RANKL and OPG in experimental periodontitis." (PMID 33673606, 2021). "In particular, GMSCs were treated with a culture containing inflammatory cytokines such as TNF-α, IL-1β, IFN-γ, IFN-α, and IL-3, and an inflammatory animal model was created in one study, ligature-induced periodontitis in mice." (PMID 33628266, 2021). "The expression levels of TNF-α stimulated by P. gingivalis LPS were suppressed by BAFF knockdown, which was consistent with the results of BAFF blockade in mouse periodontitis model." (PMID 34481478, 2021). "The populations of TNF-α- or IL-17A-producing memory CD4+ and CD8+ T cells were significantly higher in the regional lymph nodes of HFD-fed mice with periodontitis than in those of mice fed a NCD." (PMID 35069547, 2021). "IL-1, tumor necrosis factor alpha (TNF-α), and interferon gamma (IFN-γ) are important cytokines which are highly involved in the progression of periodontitis." (PMID 34566966, 2021). "We found significantly more TNF-α- or IL-17A-producing CD4+ and CD8+ T cells in the regional lymph nodes of mice with ligature-induced periodontitis than in control lymph nodes." (PMID 35069547, 2021). "Elevations in TNF-α serum level were found in both SLE mouse models and in lupus patients with periodontitis, and these elevations positively correlated with disease activity." (PMID 33861790, 2021). "In periodontitis, the GCF contains large amounts of cytokines and proinflammatory mediators such as IL-1 beta and TNF alpha that are responsible for periodontal destruction." (PMID 34502071, 2021).
periodontitis (continued). "TNF‐α, a pro‐inflammatory cytokine, has been shown to be the same in GCF in RA patients with periodontitis, periodontitis patients and healthy subjects, or increased in GCF and serum of RA patients and increased in periodontitis irrespective of RA status." (PMID 33954982, 2021). "In periodontitis, aberrant genes highlighted include interleukin-1, interleukin-6, interleukin-10, transforming growth factor-beta (TGF-β), tumor necrosis factor-α (TNF-α), interferon-gamma (IFN-γ), and matrix metalloproteinases (MMPs) among others." (PMID 33869630, 2021). "Among various inflammatory mediators, TNF-α, IL-1β, IL-6, and IFN-γ are the most effective proinflammatory cytokines during periodontitis." (PMID 32724318, 2020). "The group showed that periodontal therapy was correlated with alterations of PTGS2 gene methylation in patients with CP, while DNA methylation levels of TNF and IFNG remained unchanged in the periodontitis group after periodontal therapy." (PMID 32867386, 2020). "Significantly higher levels of serum of cytokines IL-6, TNF-α and IL-1β, IL10, IL35, and TGF-β1 were measured in patients with chronic periodontitis when compared to the healthy control group." (PMID 32604936, 2020). "Based on previous research results by our group, TNF-α and AGEs were separately added to simulate environments of simple periodontitis, T2DM, and T2DM with periodontitis in vitro." (PMID 32611833, 2020). "Diabetic rats with periodontitis show a higher expression of sclerostin, RANKL, tumor necrosis factor-α (TNFα), and IL-1β in osteocytes, which affects osteoblast and osteoclast function." (PMID 32733380, 2020). "Chronic periodontitis is responsible for the production of C-reactive protein (CRP), interleukin-1b, interleukin 6, TNF-alpha (Tumor Necrosis Factor), as well as the dissemination of these inflammatory mediators throughout the body." (PMID 33143275, 2020). "Based on the role of TNF-α and COX-2 in the pathogenesis of periodontitis, THRIL and PACER are putative contributors in this inflammatory condition." (PMID 32426538, 2020). "In different studies, it has been postulated that this cytokine exerts an anti-inflammatory effect by regulating IL-1 and TNF-α production in human granulomas and GCF of subjects with chronic periodontitis." (PMID 33218047, 2020). "The presence of proinflammatory cytokines, such as IL-1β, TNF-α, and CRP, together with the presence of β-amyloid were found in the brain tissues of mice where periodontitis was induced by the inoculation of P. gingivalis in the periodontal tissue." (PMID 32054121, 2020). "The concentration of TNF-α in GCF of periodontally healthy individuals is 2.73 ng/ml, and it increases up to 9.5 ng/ml in experimental gingivitis patients and chronic periodontitis patients." (PMID 32089705, 2020). "Accordingly, in our study, we evaluated the change in serum levels of pro-inflammatory and anti-inflammatory cytokines among periodontitis patients, and we found that they had higher significant levels of IL6, IL1b, and TNF compared to healthy individuals." (PMID 32604936, 2020). "Both JQ1 and I-BET151 were small molecule inhibitors for BET proteins and JQ1 was demonstrated to attenuate inflammation and bone destruction in experimental periodontitis via neutralizing BRD4 enrichment at NF-κB, TNF-α, c-Fos, and NFATc1." (PMID 30455393, 2019). "Immunohistochemical staining of TNF-α, IL-1β and MMP-9 in mandible sections yielded a much stronger staining intensity in gingiva and PDL area from periodontitis induced rats compared to control rats, but this was mitigated in PDT treated rats." (PMID 31160615, 2019). "mRNA expression of inflammatory cytokines IL-1β, IL-6, TNF-α and the RANKL/OPG mRNA ratio were increased in periodontitis patients compared with gingival samples of healthy controls (p < 0.05), matching the clinical diagnosis of periodontitis." (PMID 31848404, 2019).
periodontitis (continued). "Leukocyte and macrophage number and protein level of tumor necrosis factor α (TNF-α) in periodontium and serum interleukin-6 level were downregulated by HF diet in periodontitis mice (P < 0.05)." (PMID 30719451, 2019). "Consistent with previous studies, our results indicate that SHI down-regulates IL-1, IL-6, TNF-α, MMP-2, MMP-9 and COX-2 expression in LPS-stimulated hPDLCs, thus indicating the anti-inflammatory potential of SHI in the treatment of periodontitis." (PMID 30392422, 2018). "The maintenance of the inflammatory process is mediated by cytokines (TNF-α, IL-1β, IL-6, IL-8, IL-12, IL-17, IL-18, IL-23 and IFN-γ) in RA and in periodontitis." (PMID 30281626, 2018). "This study evaluated the expression of pro-inflammatory (IL-1β, IL-6, IFN-γ and TNF-α) and anti-inflammatory (IL-4 and TGF-β) cytokines in apical periodontitis lesions." (PMID 29898177, 2018). "In two recent studies conducted with women immediately after delivery, GCF levels of IL-1β, IL-6, TNF-α, and PGE2 and serum levels of TNF-α and PGE2 were significantly increased in women with periodontitis compared with periodontally healthy women." (PMID 29017560, 2017). "The objective of this study was to determine the effect of TNF-α expression of osteocytic RANKL and sclerostin in type 1 diabetes rats with periodontitis using infliximab (IFX), a TNF-α antagonist." (PMID 29240821, 2017). "It has been demonstrated that TNF-α has a role in osteoclastogenesis in mice, and recombinant TNF-α has been shown to accelerate periodontitis in rats." (PMID 28431542, 2017). "TNF-α is present at high levels in both gingival crevicular fluid (GCF) and tissues in periodontitis, where positively correlates with matrix metalloproteinases and receptor activator of nuclear factor kappa-B ligand expression." (PMID 28632755, 2017). "Previous research indicated that the expression of ICAM1 is regulated by certain inflammatory cytokines, including IL-1β and TNF-α, and that ICAM-1 plays an important role in the initial stage of periodontitis." (PMID 29091721, 2017). "We also showed overexpression of IL1B, TNFα, ICAM1, and RANKL mRNA in the palatal gingival tissues of periodontitis model rats, which is consistent with previous reports." (PMID 29091721, 2017). "In order to compare the differences of salivary BPIFA1, TNF-α, and IL-6 concentrations among T2DM/NDM patients with periodontitis at different stages, we further divided the subjects into eight subgroups." (PMID 29109737, 2017). "In an experimental periodontitis model, the expression profile of HMGB1 has been shown to be similar to those of TNF-α and IL-6, with higher expression of those cytokines occurring at day 7 and 15 followed by a decrease on day 3012." (PMID 28765610, 2017). "Based on these results, we conclude that transfection of the NF-κB decoy ODN can suppress the overexpression of the downstream factors IL-1β, TNF-α, and ICAM-1 in the palatal gingival tissues of rats with periodontitis." (PMID 29091721, 2017). "Chronic inflammation induced by P. gingivalis and P. intermedia and other bacteria in the oral cavity results in periodontitis that can affect both cellular and humoral immunity, with consequent release of cytokines such as IL-2, IFN-γ, and TNF-α." (PMID 29109737, 2017). "Besides TNF-α-mediated mechanism in the current study, decreased osteoblastogenesis by insulin/insulin like growth factor might also suppress bone formation in the type 1 diabetes with periodontitis." (PMID 29240821, 2017). "Thus, cross sectional studies have shown that the presence of periodontitis, or antibodies to common periodontal bacterial flora, are associated with an increase in a systemic proinflammatory state characterized by an increase in serum CRP; TNFα and TNFα/IL10 ratios in participants with AD." (PMID 26963387, 2016).
periodontitis (continued). "For example, SRP decreased serum tumor necrosis factor-α (TNF-α), interleukin-6 (IL-6) and C-reaction protein (CRP) levels in chronic periodontitis subjects with stable coronary heart disease." (PMID 27386384, 2016). "TNF-α, IL-1, and PGE2 also promote osteoclast activity, particularly in states of inflammatory osteolysis such as those found in periodontitis." (PMID 26065002, 2015). "Furthermore, in a clinical study comparing patients with generalized aggressive periodontitis and periodontally healthy subjects, nonsurgical periodontal therapy for ± 14 days was associated with a significant decrease in TNF-α and IL-17 serum levels in the group with periodontal disease." (PMID 26644840, 2015). "Therefore, reduction of the inflammatory mediators such as TNF-α and IL-6 (serum and/or GCF), which are also associated with both hyperlipidemia and periodontitis may provide a further contribution to a two-way relationship between periodontitis and hyperlipidemia." (PMID 26666260, 2015). "With regard to human periodontitis, an immunohistochemistry study showed increased levels of TNF-α receptor p55 and p75 expression and TNF-α positive cells in the gingival tissue from patients with adult periodontitis compared with the healthy controls." (PMID 25657893, 2015). "The present results demonstrate that diabetic patients with untreated periodontitis present increased circulating levels of markers of inflammation and proinflammatory cytokines (CRP, TNF-α and IL-6)." (PMID 26644840, 2015). "A consensus report of the 7th European Workshop on Periodontology recently highlighted interleukin (IL)-1β, IL-6, tumor necrosis factor (TNF)-α, and RANKL as important players in the periodontitis network." (PMID 26734583, 2015). "Pro-inflammatory interleukin-1β (IL-1β) and tumor necrosis factor-α (TNF-α) play a prominent role in periodontal inflammation and are elevated in gingival crevicular fluid (GCF) and in gingival tissue in periodontitis." (PMID 26241961, 2015). "Our results indicated that recombinant APN treatment decreased mRNA expression of the proinflammatory cytokines including TNF-α, IL-1, and IL-6 in WAT isolated from DIO mice induced with periodontitis (P<0.05)." (PMID 24836538, 2014). "In agreement with the ability of APN to inhibit local chronic inflammation in our experimental periodontitis DIO model, we found gene expression levels of proinflammatory cytokines including TNF-α, IL-1, and IL-6 were significantly reduced in WAT tissues." (PMID 24836538, 2014). "TNF-α and RANTES mRNA were not only expressed in the drug-induced gingival overgrowth and periodontitis but also, weakly, in the uninflamed gingival tissues." (PMID 20871770, 2010). "This study was carried out to assess the mRNA expression of TNF-α and RANTES in healthy individual, chronic periodontitis and CsAinduced gingival overgrowth tissues." (PMID 20871770, 2010). "The mRNA expression of TNF-α and RANTES in human gingival samples obtained from patients with cyclosporin-A-induced gingival overgrowth (DIGO), periodontitis and normal healthy subjects (control)." (PMID 20871770, 2010). "The level of the TNF-α and RANTES mRNA expression from periodontitis and drug-induced gingival overgrowth tissue samples were increased compared with that in the uninflamed tissues." (PMID 20871770, 2010). "The results suggest that CsAinduced gingival overgrowth tissues expressed significantly increased TNF-α and RANTES compared to control and chronic periodontitis." (PMID 20871770, 2010). "The expression of TNF-α, RANTES and β-actin in human gingival tissues with chronic periodontitis and drug-induced gingival overgrowth was examined." (PMID 20871770, 2010). "Additionally, the study's findings showed that gingival tissue in a periodontitis model had higher levels of IL1-β and TNF-α than the control group (p ≤ 0.01)." (PMID 41625272, 2026).
periodontitis (continued). "This study evaluated local and systemic levels of asprosin, tumor necrosis factor-α (TNF-α), and interleukin-6 (IL-6) in obese and normal-weight individuals with and without periodontitis." (PMID 41942957, 2026). "In the paper that compared cytokine levels for 54 periodontitis patients and 40 healthy controls, cytokines IL‐1β, IL‐4, IL‐6, IL‐10, IL‐17A, IL‐17F, IL‐21, IL‐22, IL‐23, IL‐25, IL‐31, IL‐33, IFN‐γ, sCD40L and TNF‐α were measured in saliva and serum at baseline, 3, 6 and 12 months after treatment." (PMID 41580300, 2026). "By contrast to saliva, the inflammatory markers of periodontitis patients showed no marked differences in blood plasma, except for TNF-alpha and partly IL-4." (PMID 41969371, 2026). "Periodontitis has been shown to contribute to the development and progression of NAFLD through the mediation of inflammatory cytokines, including interleukin (IL)-1β, IL-6, and TNFα." (PMID 40142822, 2025). "This study’s results indicated that GCF ESM-1 levels were elevated but not statistically significant in periodontitis patients; these levels, along with TNF-α, were considerably reduced following NSPT." (PMID 40426985, 2025). "The level of TNF-α in gingivitis sites was significantly lower than in periodontitis sites (p = 0.038), but there was no statistically significant change when comparing healthy sites to gingivitis sites and periodontitis sites." (PMID 41303313, 2025). "In addition, in the LR, LRP2, and LRP5 groups, lower levels of TNF-α and IL-1β were observed in both tissue and serum samples, similar to the finding that TNF-α and IL-1β levels were correlated with the degree of periodontitis and decreased after SRP." (PMID 39941567, 2025). "Also, the mean levels of TNF-α and IL-1β in the saliva and GCF of patients with periodontitis were significantly higher than patients with gingivitis (P<0.05)." (PMID 40265034, 2025). "Periodontitis affects endothelial function through systemic inflammation involving mediators such as CRP, IL-6, and TNF-α that can affect endothelial function, which may contribute to hypertension development." (PMID 40735233, 2025). "Cytokines, such as interleukin-1β (IL-1β), tumor necrosis factor-alpha (TNF-α), and acute-phase proteins, including CRP, which are secreted during periodontitis, enhance systemic inflammation, which in turn aggravates endothelial dysfunction and plaque formation." (PMID 40418274, 2025). "This study explored the relationship between ghrelin, TNF-α levels, and periodontal parameters in individuals with periodontitis, with and without T2DM." (PMID 41280962, 2025). "Systemically, chronic low-grade inflammation from periodontitis elevates circulating RANKL and proinflammatory cytokines (IL-1β, IL-6, and TNF-α), which may exacerbate skeletal resorption in osteoporosis-prone individuals." (PMID 41466921, 2025). "Immune-inflammatory agents, namely CRP, TNF-α, CXCL10, IL-6, IL-18, sVCAM-1, sICAM-1, IP-10 and MCP-1, have been found in high concentrations in the circulating blood of pregnant individuals diagnosed with preeclampsia who also have periodontitis." (PMID 41394354, 2025). "have found that the levels of periodontal clinical indices, including PI, PD, AL, GI, PGRN, TNF-α, and IL-1β, in the gingival crevicular fluid of patients with Chronic Periodontitis (CP) were significantly increased, and the PGRN/TNF-α ratio was significantly reduced." (PMID 40290306, 2025). "Those with periodontitis had a significantly higher rate of cognitive decline, along with elevated levels of the pro-inflammatory cytokines TNF-α and IL-10, although not of IgG against P. gingivalis." (PMID 40231144, 2025). "Furthermore, the use of LDN57444, a specific UCH‐L1 inhibitor, enhanced the osteogenesis of PDLSCs exposed to tumour necrosis factor alpha (TNF‐α) or IL‐1β, suggesting a destructive role of UCH‐L1 in periodontitis progression." (PMID 39626954, 2025).